GZMB (granzyme B)
Diseases named in the same sentence as GZMB in open-access papers (continued):
Sharing a sentence is not in itself a finding about the gene and the disease.
tumor (continued). "However, in the TME, hypoxia-induced autophagy in tumor cells has been shown to impair the NK cell response and degrade NK-derived granzyme B that enters the tumor cell through endocytosis, allowing the tumor to escape NK-mediated killing." (PMID 31396523, 2019). "Significant higher number of Granzyme B (GZMB) positive cells was detected in MC38 tumors from mice treated with the combined treatment (p = 0.016) while anti-PD-1 determined a modest but significant increase of tumor-infiltrating GZMB positive cells (p = 0.035)." (PMID 31661001, 2019). "Moreover, the percentage of granzyme B+ cells in tumor-infiltrating NKG2A+ CD8+ T cells was significantly decreased compared with that in paired normal tissue." (PMID 32010126, 2019). "Moreover, our findings establish that niclosamide potentiates anti-PD-L1 blockade response in vitro as well as in syngeneic tumor models, which correlates with an increased content of TILs and enhanced secretion of Granzyme B and TNF-α from cytotoxic T cells." (PMID 31511071, 2019). "The level of granzyme B, the effector molecule of tumour-infiltrating NK cells, was also decreased." (PMID 31324197, 2019). "We next investigated whether tumor growth delay in the unirradiated tumors was mediated by immune activation by analyzing the expression of CD8+/GzmB+ cells and CD4/Foxp3+ cells in TILs by flow cytometry." (PMID 30774761, 2019). "TNF-α, granzyme B, and perforin were all downregulated in cells lacking JAK1; this was rescued by the re-expression of codon-optimized JAK1, implying that JAK1 deficiency prevents killing by tumor-specific T-cells." (PMID 30837996, 2019). "Another group found that while there were detectable T cell responses to tumor-associated antigens, responses declined with advancing disease and tumor antigen-specific CD8+ T cells were dysfunctional with low production of IFNγ, Granzyme B, and perforin." (PMID 31627733, 2019). "The microarray data revealed 728 distinctly regulated genes between two populations and the top highly expressed genes (IL2RB, GZMA, GZMB, EMR4, PRF1, CX3CR1, STAT1, and TLR9) in lung-derived Ly6C+ cells from EMT6 tumor-bearing mice are associated with effector T-cell function." (PMID 30926774, 2019). "Granzyme B (GRZB) positive immune cells were evaluated in the whole tumor sections." (PMID 31661001, 2019). "We also showed that most of tumor-infiltrated neutrophils (CD66b+ cells) expressed GZMB." (PMID 29983866, 2018). "Thus, following reward system activation, MDSCs exhibited an attenuated immunosuppressive profile, which manifested in vivo by increased expression of Granzyme B by tumor CD8 T cells." (PMID 30006573, 2018). "In addition, the fraction of granzyme B-expressing CD8+ T cells was significantly lower in tumor compared to PBMC (p = 0.038)." (PMID 29966014, 2018). "We hypothesized that WEE1 kinase inhibition could sensitize tumor cells to granzyme B-dependent NK killing." (PMID 29925431, 2018). "However, our studies with in vivo mouse tumor models showed that GzmB is important for natural Treg cell-mediated suppression of anti-tumor response." (PMID 30631325, 2018). "In addition to the significant increase in the number of CD8+ TILs, there is a significant increase in the expression of IFNγ and granzyme B in CD8+ cells in tumor tissues after being incubated with VentX-modified TAMs." (PMID 29872044, 2018). "Similarly, there was robust granzyme B staining localizing to the tumors; affirming the presence of cytotoxic immune cells within the tumor." (PMID 29930558, 2018). "This seems to be important for the anti-tumor function of neutrophils mediated by the GZMB." (PMID 29983866, 2018). "Additionally, there was a significant increase in tumor intracellular Granzyme B expression as measured by flow cytometry following treatment with chemotherapy and T4 cells." (PMID 30167862, 2018). "Impaired immune response via lower CD8+ and/or granzyme B+ T cells to control tumor growth or spread may also contribute." (PMID 30524961, 2018).
tumor (continued). "In comparison to placebo, QBKPN administration increased granzyme B (GzmB), granzyme A (GzmA), and perforin (Prf1) expression in the lungs of B16F10 tumor-bearing mice, which were associated with a decrease in tumor burden." (PMID 29399400, 2018). "Importantly, intratumoral granzyme B+ cells were visualized; thereby, confirming the presence of cytotoxic cells within the tumor." (PMID 29930558, 2018). "It is also possible that GZMB extracellular effects seems to be pro-inflammatory that a GZMB pro drug could be used to recruit local immune cells to the tumor and help facilitate an anti-tumor immune response." (PMID 29854290, 2018). "We observed a 50% decrease of granzyme B+/perforin+ of tumor-derived CD8+ T cells compared to PBMC." (PMID 29966014, 2018). "X4P-001 alone increased infiltration of CD8+ T cells, granzyme B signal, antigen- processing and presentation machinery, such as HLA-DR, and both Tumor Inflammatory Signature (TIS) and IFN- gamma gene expression signature scores in the TME of select patients with paired evaluable biopsies." (PMID 30400835, 2018). "It was initially considered that tumor cells are killed by granzyme B and perforin secretion." (PMID 29515106, 2018). "Furthermore, intracellular Granzyme B levels were significantly reduced in tumor cells treated with chemotherapy and 3-MA followed by T4 cells, suggesting that the “gateway” had been closed." (PMID 30167862, 2018). "Deficiency of Eomes in T cells also dampened effector cytokine (IFN-γ and TNF-α) production and cytotoxicity (marked by surface CD107a expression and Granzyme B production) of CD8+ T cells in the tumor, although effector functions of CD8+ T cells in spleen and TDLN was not affected." (PMID 30619337, 2018). "GzmB-mediated activation-induced T cell death may account for the different anti-tumor immune responses between WT and GzmB−/− CD8+ T cells." (PMID 30631325, 2018). "Lymphocytes were firmly attached to dying-tumor cells containing Granzyme-B granules." (PMID 29774030, 2018). "Loss of EBNA3C expression also resulted in an increased number of tumor-infiltrating T cells as determined by IHC staining, and RNA-seq data showed increased expression of genes associated with cytotoxic T cells (including CD8, perforin, and granzyme B)." (PMID 30125329, 2018). "Furthermore, we investigated the concentrations of secreted soluble granzyme B and perforin in the culture supernatant by ELISA after seven days of tumor antigen activation." (PMID 29966014, 2018). "Granzyme B expression in neutrophils could be induced by the lipid A analog but also by some of the cytokines that were detected in the tumor microenvironment." (PMID 29983866, 2018). "Granzyme B positivity was only increased in irradiated tumours depleted of macrophages." (PMID 30442705, 2018). "Furthermore, our data revealed increased expression of interferon gamma (Ifng) and granzyme B (Gzmb) in female LR/Stat3Δ/Δ mice, suggesting anti-tumor immune responses in Stat3-deleted females." (PMID 30389925, 2018). "Lastly, we also showed that a BCC tumor is infiltrated by a higher number of negative regulatory immune cells which might also impair the activity of CD8+/ Granzyme B+ T cells, undermining the efficacy of PD-1 blockade." (PMID 30458852, 2018). "More recent reports suggested that granzyme B may contribute to suppression of anti-T cell responses and may be highly expressed in Tregs in the tumor microenvironment." (PMID 28603578, 2017). "Further building on these results, we investigated whether the increased recruitment of granzyme B+ cells could also be translated into functional cytotoxic activity against tumor cells." (PMID 28099143, 2017). "Future studies will need to identify the specific B cell subset-derived immune responses against CAC in MDR1A deficiency, which may include several tumoricidal mechanisms, such as production of granzyme B and anti-tumor antibodies." (PMID 28686677, 2017).
tumor (continued). "Interestingly, independent expression of HTLV-1 oncogenes Tax and HBZ by the same promoter, Granzyme B, resulted in very different tumor phenotypes in transgenic mice." (PMID 29050201, 2017). "To test the effects of beta blockers on the chemokine environment in tumors of RRS-exposed animals, we examined the expression of genes that are characteristic of either immune suppression (Foxp3, CCL22) or effector anti-tumor immunity (Granzyme B, CCL5, IFN-γ, CXCL9, CXCL10 and CXCL11)." (PMID 28603578, 2017). "This is not only due to their direct tumor cell-killing function via granzyme B/perforin pathway and other death-receptor pathways, but also due to their ability to secrete a plethora of proinflammatory cytokines and chemokines that regulate and promote innate and adaptive immune response." (PMID 28603525, 2017). "Moreover, there were fewer IFN-γ+ granzyme B+ antigen-specific CD8+ T cells from the tumours of Grail−/−Il21−/− mice compared to Grail−/− mice, supporting the role of IL-21R signalling in Grail−/− CD8+ T-cell expansion and function." (PMID 28798332, 2017). "To further understand the role of adaptive immunity in the tumor tissue, we investigated the impact of RRS on tumor weight and on immune suppression markers (Foxp3, CCL22), as well as markers for anti-tumor immunity (Granzyme B, CCL5, IFN-γ, CXCL9, CXCL10 and CXCL11)." (PMID 28603578, 2017). "Additionally, while granzyme B and interferon-y are both widely used for measuring tumor-specific responses, ELISpot results suggest that granzyme B is the more specific indicator of CTL and NK cytotoxic ability." (PMID 28415565, 2017). "To test whether reduction of granzyme B+ cells correlate with changes in tumor antigen load in TLO from advanced and evanescent carcinoma patients, we stained prostate sections with antibodies against PCNA, PSCA, and plasma cell antigen." (PMID 28567040, 2017). "The PBT anti-tumor effect was accompanied by an increase in granzyme B+, IFN-γ+ CD8+ T-cells and a decrease in immunosuppressive tumor infiltrating cells including Gr-1+CD11b+ myeloid derived suppressor cells (MDSCs), CD4+CD25+ Tregs, and CD206+F4/80+ M2 macrophages." (PMID 29137411, 2017). "Indeed, hypoxic stress inside the tumor microenvironment impairs NK cell cytotoxicity, probably through inhibiting expression of activating receptors, granzyme B and perforin." (PMID 29163816, 2017). "CD8+ effector T cells can directly kill tumor cells by releasing perforin, granzyme B and IFNγ." (PMID 28220815, 2017). "Interestingly, apart from the enhancement of antigen-presenting capacity of DCs, irradiated tumor cells can induce the expression of granzyme B and perforin in DCs and directly stimulate DCs cytotoxicity to kill tumor cells." (PMID 28603525, 2017). "However, reprogrammed T cells also produce perforin and granzyme B, allowing them to induce apoptosis in tumor cells before they begin to up-regulate PD-L1 mediated by IFN-γ." (PMID 26928306, 2016). "However, there were significantly more granzyme B-positive CD8+ T cells in the tumours treated with PEG2k-Fmoc-NLG(L) or PTX/PEG2k-Fmoc-NLG(L) compared with Taxol-treated tumours." (PMID 27819653, 2016). "In accord with this finding, RLH activation with Poly(I:C) augmented granzyme B and perforin gene expression in lungs from tumor challenged mice and these effects were partially ameliorated when the levels of Chi3l1/YKL-40 were augmented using transgenic methodology." (PMID 27198666, 2016). "Here, we further demonstrated EBI3 not only promoted CRC cell proliferation through the gp130/Stat3 axis, but also restrained tumor infiltrating Granzyme B+ CTLs and IFN-γ+ CTLs production to promote tumor growth in CRC by EBI3 blocking peptide in vitro and in vivo." (PMID 27247488, 2016). "However, our recent study demonstrated that GzmB-mediated damage of CD8+ T cells diminished their graft-versus-tumor (GVT) activity." (PMID 27774524, 2016).
tumor (continued). "The cell death-inducing serine protease granzyme B has been found to directly interact with membrane Hsp70 on tumor cells, as determined by different methods including matrix-laser desorption ionization time to flight mass peptide finger printing (MALDI-TOF), Western blot, and flow cytometry." (PMID 27199993, 2016). "The mechanism how Hsp70 preactivated NK cells lyse membrane Hsp70+ tumor cells could be identified as granzyme B-mediated apoptosis." (PMID 27199993, 2016). "Therefore, to verify the cytolytic activity of the TILs seen in these tumor samples, GzmB+ cell infiltration was analyzed." (PMID 27310868, 2016). "Therefore, the tumor samples stained for GzmB+ cell infiltration were reanalyzed at the IB in the samples that contained an IB (n = 177; 82 AA; 95 CA)." (PMID 27310868, 2016). "To determine whether natural killer cells participated in specific anti-tumor response, we measured the concentrations of granzyme B and perforin released from the natural killer cells harvested from mice immunized with HSP70-P/AFP-P and the controls." (PMID 27713135, 2016). "Moreover, tumours treated with PTX/PEG2k-Fmoc-NLG(L) had more granzyme B-producing CD8+ T cells than the tumours treated with Taxol, suggesting IDO inhibition can still enhance antitumour T-cell immune responses in spite of repeated chemotherapy." (PMID 27819653, 2016). "Then, we isolated CRC cells and tumor infiltrating lymphocytes (TIL) from 10 CRC patients tissues to assess the Granzyme B, IFN-γ, EBI3, IL-27p28, and IL-12p35 production and proliferation of TILs, Tregs after coculture with autologous CRC cells blocked by EBI3 blocking peptide." (PMID 27247488, 2016). "In keeping with this, it is tempting to speculate that GZMB is selectively degraded by autophagy in hypoxic tumor cells." (PMID 26910842, 2016). "In addition, the mRNA levels of effector molecules such as IFNγ and granzyme-B in the lungs were reduced after tumor injection (P <0.001)." (PMID 27036297, 2016). "In tumor lesions, the local expression of CCL5 and CXCL10 was positively associated with the expression of the CD8+ T lymphocyte markers CD8 and Granzyme B (RCD8 = 0.2338, pCD8 < 0.01, RGranB = 0.5517, pGranB < 0.001; RCD8 = 0.2972, pCD8 < 0.005, RGranB = 0.3204, pGranB < 0.001)." (PMID 26317795, 2015). "An increased expression density of the C-type lectin receptor CD94 has been identified as a useful surrogate for the cytolytic activity of NK cells, and granzyme B-mediated apoptosis was found to be responsible for the killing of tumor cells presenting Hsp70 on their cell surface." (PMID 25926832, 2015). "An IL-17E enhanced cytotoxicity of TIL-B cells could be discussed as well as it was already demonstrated that B cells stimulated with IL-21 can secrete granzyme B and could have a direct cytotoxicity against tumor cells." (PMID 26154409, 2015). "The higher expression of TNFSF10 and GZMB in CIKIL-2 may account for the greater tumor cytotoxic efficiency of CIKIL-2 than CIKIL-15." (PMID 25826780, 2015). "For example, type I IFN endogenously produced by innate cells can bridge adaptive immune responses by upregulating MHC molecule expression on APCs, and enhancing Granzyme B-mediated tumor cytotoxicity of tumor infiltrated CD8+ T cells, all of which are supported by our data." (PMID 25796556, 2015). "After 20 days, we dissociated skin-draining lymph nodes and re-stimulated lymph node lymphocytes with Her2/neu peptides, mitomycin C-treated BR5FVB1 tumor cells, or BR5FVB1 tumor cell lysate, and performed flow cytometric analysis for the presence of Granzyme B-generating CD4+ and CD8+ T cells." (PMID 24565018, 2014). "Immunohistochemistry showed staining for CD3ɛ(−), CD20(−), CD45(+), CD30(+) and CD56(+) presented with positive staining for certain tumor cells, granzyme B(+), activin receptor-like kinase 1(−), Ki-67(+) and Epstein-Barr virus-encoded small RNA(+), which indicated nasal-type extranodal NKTL." (PMID 24765148, 2014).
tumor (continued). "Moreover, there were significantly fewer perforin-, granzyme B- and TNFα-producing cells in the tumor of mice receiving STZ-diabetic P14 CD8+ effector cells than STZ-non-diabetic group." (PMID 25390652, 2014). "In addition, we provided mechanistic evidence that the activation of autophagy under hypoxia led to the degradation of NK-derived granzyme B, making hypoxic tumor cells less sensitive to NK-mediated killing." (PMID 24400010, 2013). "It is believed that IFN-α, induced by IFI27, stimulates myeloid dendritic cells to activate IL-12, which in turn prompts T-cells to secrete IFN-γ, and arms NK cells and CD8+ cytotoxic T lymphocytes (CTL) with perforin A and granzyme B for killing tumor targets." (PMID 23959120, 2013). "The tumor cells were strongly expressed CD3ε, CD56, TIA-1, granzyme B and EBV-encoded RNAs." (PMID 23773344, 2013). "It is well recognized that cytotoxic T lymphocytes (CD8+ T cells) are crucial components of antitumour immunity, since activated CD8+ T cells can directly kill tumour cells by the release of granules including lytic components such as perforin and enzymatic proteases (like granzyme B, GZMB)." (PMID 23349906, 2013). "On the contrary, internalized killer cells from GzmB-deficient mice underwent a typical non-apoptotic entotic cell-in-cell death similar to that of non-cytotoxic immune cells or tumor cells." (PMID 24113190, 2013). "Thus, both CD8+ and CD4+ T-cell populations in drLN expressed pro-inflammatory cytokines and GzmB in response to tumor challenge, but the CD4+ T-cell response initiated earlier and the magnitude of the response was higher than the CD8+ T-cell response." (PMID 22890822, 2013). "To analyze whether the increased expression of GzmB correlated with improved tumor-specific lysis of target cells after Treg depletion, we performed a series of in vivo killing experiments." (PMID 22890822, 2013). "GzmB was restrained in the granules of internalized NK92 at the early time point (2 h), as GzmB was colocalized with lysosomal-associated membrane protein 1 (LAMP1) in internalized NK92 cells after entering MCF7 tumor cells (upper row)." (PMID 24113190, 2013). "Moreover, we showed that, in contrast to AA, the inhibition of cancer cell invasion paralleled DHA-induced downmodulation of the tumor-expressed chymotrypsin-like serine protease granzyme B (GrB)." (PMID 23762838, 2013). "However, it is now clear that CD4+ T-cell can kill tumor cells through direct cell contact via FasL- and TRAIL-dependent pathways, as well as through the perforin/granzyme B pathway, which is classically associated with cytotoxic CD8+ T-cells." (PMID 26344346, 2013). "Quantification of tumor-infiltrating CD8+ T cells expressing Granzyme-B or binding H-2Kb-OVA tetramer revealed that vaccination with necrotic cell-primed MFG-E8 KO DC increased the frequency of OVA-specific CD8+ cytotoxic T lymphocytes in tumor tissues." (PMID 22761839, 2012). "Immunohistochemically, the tumor cells were cytokeratin -, vimentin +, CD3+, CD45RO+, CD5-, CD7-, CD4-, CD8-, CD10-, CD20-, CD30-, CD79a-, CD138-, CD56-, granzyme B-, TIA-1 cytotoxic granule-associated RNA binding protein (TIA-1) + and ALK-." (PMID 22931631, 2012). "Furthermore, Mam-A2.4 specific CD8 T cells express more granzyme B, localized to the tumor site in higher frequencies than CD8 T cells specific for the other Mam-A epitopes and resembled memory cell in that they expressed high levels of CD127 and CD122." (PMID 22911764, 2012). "It is known that T cells kill tumours by the perforin/granzyme B and the Fas/FasL pathways." (PMID 19953093, 2010). "Our group has identified a membrane form Hsp70 on tumor cells as a tumor-specific recognition structure for a perforin-independent, granzyme B-mediated attack by allogeneic and autologous NK cells that have been pre-stimulated with Hsp70 peptide TKD plus low dose IL-2." (PMID 21179573, 2010).